MIR651 (microRNA 651)
Synonyms: hsa-mir-651; MIRN651; mir-651
Gene: MicroRNA gene on chromosome X (8,126,965 to 8,127,061, forward strand). Ensembl gene ENSG00000207628.
Gene Ontology:
Biological process: miRNA-mediated post-transcriptional gene silencing
Homologues: Orthologues: chimpanzee ptr-mir-651 (99% identical), macaque mml-mir-651 (95% identical).